CD28 (CD28 molecule)
Diseases named in the same sentence as CD28 in open-access papers (continued):
Sharing a sentence is not in itself a finding about the gene and the disease.
tumor (continued). "Specifically, it was observed that highly immunogenic tumors had a higher proportion of EMRA CD8+T cells that were negative for CD27/CD28 expression at the tumor site." (PMID 40426949, 2025). "Treatment with anti‐CD3/CD28 increased the frequency of CD137+/CD8+ T cells and induced cytokine responses dominated by IFNγ, IL‐2, and Granzyme B. While both non‐tumor and tumor‐border tissue responded to anti‐CD3/CD28, the intensities of immune responses were highly varied." (PMID 40952312, 2025). "This design efficiently bridges T cells and tumor cells, triggering immune synapse formation and cytotoxic activity without requiring co-stimulatory signals like CD28 or IL-2." (PMID 39982231, 2025). "Consistently across two tumor models, the NKG2D/CD28&MSLN CAR-T group exhibited a higher CAR-T cell count per microliter of blood at both time points, with a greater proportion of naïve T cells and lower PD-1 expression compared to the traditional CAR-T group." (PMID 40181405, 2025). "Furthermore, given the widespread expression of NKG2D ligands across various tumor types, the NKG2D/CD28 CCR exhibits broad applicability and has the potential to enhance antitumor responses when utilized in conjunction with a diverse array of CAR constructs." (PMID 40181405, 2025). "More recently, a significant advance in harnessing costimulation as a cancer immunotherapy has been the development of nonsuperagonistic and tumor-targeted CD28 bispecific antibodies that require a separate tumor-associated Signal 1 for efficacy." (PMID 39301613, 2025). "Similarly, agents modulating innate immunity, such as co-stimulatory receptor agonists like CD28 and OX40, represent promising strategies, especially when paired with checkpoint inhibitors to amplify anti-tumor immunity." (PMID 39857682, 2025). "Currently, the existing CD28 modifications have been successful, but CD28-based CAR-T cells face much greater complexity in real human tumor environments compared to in vitro or mouse tumor models." (PMID 40181986, 2025). "However, PKM2KO CD8 TE cells were unable to fully induce IFNγ expression or control tumor growth, similar to ARS2KO and CD28 mutant T cells." (PMID 38233562, 2024). "However, this advantage can be lost upon transition to the NSCLC tumor site, akin to PD1+CD28− T cells expressing ICOS." (PMID 39684559, 2024). "However, after CD80 binds to CD28, the AICD of T cells can be avoided, leading to more durable anti-tumor activity of T cells." (PMID 39575257, 2024). "In the tumor microenvironment, the PD-1 receptor is highly N-glycosylated in T cells, thereby maintaining PD-1 stability and interaction with the PD-L1 ligand expressed in tumor cells and dampening the activity of T-cell receptor (TCR)/CD28) signals." (PMID 38474359, 2024). "Since tumor-infiltrating lymphocytes (TILs) and macrophages can be detected in the tumor tissue of patients with cSCC and BCC, elucidation of CD28 and CD86 expression within the TME may be crucial." (PMID 39329753, 2024). "The third-generation CAR is based on the second-generation with the addition of a co-stimulatory molecule, mainly CD28 and CD137; it confers stronger cytokine release and tumor-killing ability, but is also prone to promoting the phenomenon of activation-induced cell death." (PMID 39872520, 2024). "The anti-tumor functionality of this combination was compared against academic conventional anti-CD19 CAR (CAR19; ARI-0001 CAR-T) and second-generation mSA2-UniCARs based on 4-1BB or CD28." (PMID 39364400, 2024). "T cells armored with GzB-IL18 produced significantly more TNF-⍺ than those with pro-IL18 or no armoring when stimulated on tumor cell monolayers or with CD3+CD28 crosslinking." (PMID 38745414, 2024). "These effector T cells from PBMCs treated with CD3 and CD28 antibodies could secrete IFN-γ and TNF-α to act as cytotoxic cytokines together with granzyme B and perforin to initiate apoptosis in tumor cells, thereby killing cancer cells." (PMID 38321486, 2024).
tumor (continued). "We found that replacing the CD8 hinge and transmembrane domain (HTM) and the 4-1BB co-stimulatory domain (CSD) of our recently reported clinical grade FGFR4 targeting CAR with CD28 HTM and CSD resulted in increased cytotoxicity in vitro and improved anti-tumor efficacy in vivo." (PMID 39043633, 2024). "Therefore, the aim of this study is to analyze the TME of cSCC and BCC by tissue microarray (TMA) immunohistochemistry (IHC) for PD-1, PD-L1, CD28, and CD86 expression in the invasive front as well as in the core of both tumor entities." (PMID 39329753, 2024). "Co-stimulatory molecules, such as CD28, may facilitate CAR T cell activation and survival at tumor sites." (PMID 38789450, 2024). "The activated T cells could increase the production of IFNγ and IL-2, which in turn boosting anti-tumor immunity via TCR and CD28 signaling." (PMID 39218939, 2024). "The abnormal decrease of CD28 mRNA content suggests that the body lacks an effective second signal to activate CD8+CTL cells, which allows the tumor to evade the host immune surveillance and tumor immune escape." (PMID 38415245, 2024). "To determine whether TAMos have the potential to directly affect TM cell differentiation, we sorted TAMos and TANs from spleens of LLC tumor‐bearing mice and cocultured them with CD8+ T cells under activation of anti‐CD3 and anti‐CD28 antibodies." (PMID 38386350, 2024). "Tumours from PBS and Salmonella-treated mice were subjected to α-CD3 and α-CD28 stimulation ex vivo, and Nr4a3-Timer was measured in T cells, with the hypothesis of dysfunctional activation." (PMID 39558103, 2024). "Furthermore, CD28 is upregulated on CD8+ PD1hi HCC TILs compared to the PD1- and PD1int compartments thereby potentially delineating tumour-reactive TILs." (PMID 38440738, 2024). "While a complex phenotype in the context of a tumor or infection, T-cell exhaustion can be replicated in culture models by repeatedly exposing primary T cells to antigen or CD3/CD28 activation, and has been used for discovery of mediators of the exhausted state." (PMID 39689157, 2024). "To evaluate the role of USP7 on cancer cell growth under conditions where cancer cells are interacting with other TME components, we assessed the response of 3D tumour spheroids composed of cancer cells, fibroblasts and CD3/CD28‐activated immune cells to treatment with the USP7 inhibitor." (PMID 38602256, 2024). "Combination of RT with CTLA-4 or PD-1 blockade, which enables CD28 costimulation, further increased this Treg response and failed to improve tumor control." (PMID 38349740, 2024). "In cSCC, PD-1, PD-L1, and CD86 showed a significant increase of expression within the invasive front as compared to the tumor core, in contrast to CD28, which did not." (PMID 39329753, 2024). "GzB-IL18-armored T cells produced significantly more IL2 in response to CD3+CD28 crosslinking, but not tumor cells." (PMID 38745414, 2024). "An ex vivo experiment using T cells from tumor-draining lymph nodes (LNs) demonstrated that recombinant Sema6D (rSema6D) inhibited T cell activation and proliferation induced by anti-CD3/anti-CD28 stimulation, and this inhibitory effect was partially decreased in Plxna4-KO T cells." (PMID 38329122, 2024). "Local intracranial delivery of HER2 CAR T cells with either a 4-1BB or CD28 costimulatory domain eliminated brain metastases and extended survival past 100 days post tumor implantation, whereas control mice did not survive past 35 days of treatment." (PMID 38803496, 2024). "Consistent with the regulon profile, tumor-reactive T cells exhibited higher expression of pro-inflammatory effector molecules such as IFNG, TNF, and PRF1 and lower expression of genes like LBT, CD27, and CD28." (PMID 39243082, 2024). "Thus, within the tumor, the CD80 is more likely to engage CTLA4 than CD28, thereby dampening the function of T cells at attacking the tumor." (PMID 39575257, 2024).
tumor (continued). "Nonetheless, we did not detect activation of pro-IL18 following CD3+CD28 crosslinking or tumor cell exposure in any of the CAR T cell populations we studied." (PMID 38745414, 2024). "induced chronic T cell receptor (TCR) signaling in vitro by stimulating T cells with anti-CD3 and anti-CD28 antibodies, and Trefny and colleagues repetitively stimulated NY-ESO-1 TCR-T cells using human leukocyte antigen-A2-positive T2 tumor cells loaded with NY-ESO-1 peptides." (PMID 39657666, 2024). "T cells expressing a CD19 specific TRuC eliminated tumor cells in an antigen specific fashion and showed superior therapeutic efficacy in mice bearing CD19+ lymphoma cells as compared to canonical second generation CARs with either CD28 or 4-1BB costimulation." (PMID 38090558, 2023). "T cells were found to be localizing selectively around a distinct malignant duct located center-left of the tissue section, with attributed genes such as immune checkpoint costimulatory receptor CD28, as well as IFIT3, CCL5, and PLAAT4 implicating an active anti-tumor immune response." (PMID 36906603, 2023). "4-1BB-CD3zeta CAR-T cells expressed genes involved in T-cell memory program and showed persistent anti-tumor activity in mouse lymphoma models, while CD28-CD3zeta CAR-T cells failed to produce long-term effects." (PMID 37398660, 2023). "In draining cervical lymph nodes, where T cell tumor immune responses are generated during HNSCC, conventional CD3/CD28 restimulation produced significantly increased T cell proliferation in tumor-bearing mice compared to non-tumor-bearing control mice." (PMID 37444444, 2023). "In addition, researchers reported the anti-tumor properties and superior survival following the administration of CD19-CIKZ-CAR NKT cells along with the CD28 endodomain in B-cell lymphoma mouse models." (PMID 37158883, 2023). "However, despite the functional decline, PD1+CD28− T cells showed residual functional fitness at the tumor site, as revealed by the slight but significant advantage over PD1+CD28+ T cells in terms of GrzB production." (PMID 37898752, 2023). "Additionally, the analysis of the CGGA and TCGA databases also showed that CDCA7 was closely related to several tumor-related suppressors, including CD80, CD276, CD28, PDCD1LG2, and TNFSF4, which contribute to tumor development via multiple mechanisms." (PMID 37510310, 2023). "In contrast, lymph node cells activated by CD3/CD28 antibodies showed elevated amounts of IFN-γ tumor-bearing mice, compared to non-tumor-bearing mice." (PMID 37444444, 2023). "CD28-driven "signal 2" is critical for naïve CD8+ T cell responses to dendritic cell (DC)-presented weak antigens, including non-mutated tumor-associated antigens (TAAs)." (PMID 37886562, 2023). "The production of IL-6, capable of promoting tumor growth, was found to be increased in lymph node cells from tumor-bearing mice stimulated with CD3/CD28 antibodies compared to non-tumor-bearing mice in both LY2 and MOC2 HNSCC models." (PMID 37444444, 2023). "In vivo mouse tumour models, compared with anti-CLDN18.2, anti-CLDN18.2-anti-CD28 showed a greater increase in the percentage of CD8+ T cells and higher expression of CD69 on CD8+ T cells in tumour tissues as well as a greater reduction in tumour burden." (PMID 36969060, 2023). "Double positive (TIGIT+CTLA-4+) (IR-9) and triple positive (TIGIT+CTLA-4+TIM-3+) (IR-12) were highest among PD1+CD28+ T cells in periphery and did not increase in the tumor." (PMID 37898752, 2023). "CD3/CD28 stimulated lymph node cells produced slightly higher but not significant levels of IL-4 in tumor-bearing compared to non-tumor-bearing mice in both LY2 and MOC2 HNSCC models." (PMID 37444444, 2023). "Notably, we revealed that in CD28− T cells, ICOS plays conflicting roles in the periphery relative to the tumor site." (PMID 37898752, 2023).
tumor (continued). "In order to enhance the efficacy of CAR-T cell immunotherapy in solid tumors, researchers have developed a microrobot that utilizes immunomagnetic beads coated with anti-CD3 and CD28 antibodies to promote the proliferation and activation of CAR-T cells in the tumor microenvironment." (PMID 37781535, 2023). "To get further insight into relationship with cell states during proliferation, we isolated all tumor-infiltrating immune cells from WT mice, treated those with anti-CD3 and anti-CD28, and assessed how IFNγ sensing affected stem-like and exhausted T cells proportion ex vivo." (PMID 36658158, 2023). "Remarkably, at the tumor site we found that high level of PD1 selectively impairs functionality in terms of IFN-γ production only in the absence of CD28." (PMID 37898752, 2023). "In addition, we detected soluble mIL-15 in the supernatants of both transduced Hepa1-6 tumor cells and CD3/CD28 Ab-activated H9 CAR-IL15 T cells, whereas H9 CAR-IL15 T cells produced only moderate mIL-15 upon stimulation with CLDN18.2-expressing tumor cells." (PMID 37564658, 2023). "For example, unlike CAR-T cells, in CAR-NKT cells, CD28 was suitable for proliferation, tumor-killing function, and survival." (PMID 37158883, 2023). "CD28 is advocated as a key determinant in CD8+ T cells with different functional states in the signatures identified, detected in both peripheral blood and tumor site, thus likely providing feasible biomarkers of ICB response." (PMID 37898752, 2023). "Notably, CXCR5 frequency increased in all subsets with the transition to the tumor, maintaining the highest expression in PD1+CD28+ cells." (PMID 37898752, 2023). "Binding of vitamin D to VDR resulted in decreased expression of immune checkpoint inhibitors (PD-1, TIGIT, and Tim-3) and increased expression of the co-stimulatory molecule CD28 on CD8+ T cells, which increased their cytokine production and anti-tumor activity." (PMID 37175993, 2023). "Differently, the PD1+CD28− T-cell subset, after a substantial rise at NT, did not further increase in the tumor, where its frequency was significantly lower than the CD28+ counterpart (19% vs 29.5%, P = 0.007)." (PMID 37898752, 2023). "Cluster4 (SELL+CD28+) was found almost exclusively in peripheral blood, strongly declined in the NT and was absent at the tumor site." (PMID 37898752, 2023). "Furthermore, lymphatic invasion—a clinical tumor characteristic—of immune genes, including CD27, CD48, and CD28, as well as infiltration of CD8+ T cells exhibited a positive and substantial connection with LCK expression (in terms of immune cells)." (PMID 37773310, 2023). "In our pre-treatment analysis, we identified that responders showed a higher frequency of proliferating CD28-expressing CD8 T cells as well as proliferating CD4 conventional T cells, suggestive of ongoing immunity, potentially encompassing anti-tumour immune responses." (PMID 36818683, 2023). "In addition, a low expression of IL12RB1, CD28, CCL3, and GZMA before treatment in the p16- tumour group conferred a higher rate of failure." (PMID 36835246, 2023). "Remarkably, in PD1+CD28− CD8+ T cells, ICOS was associated with highest polyfunctionality in periphery but was not beneficial at the tumor site, while it did not provide advantage to the CD28+ subgroup in any district." (PMID 37898752, 2023). "Differently, in the absence of CD28, the low frequencies of double and triple positive IRs gradually increased in the transition to the tumor." (PMID 37898752, 2023). "So far, HVEM has only been reported once as a co-stimulatory domain in CAR-T cells, with HVEM G2 CAR-T cells exhibiting enhanced anti-tumor cytotoxicity and pro-inflammatory cytokine production (e.g., IL-2, TNF-α, and IFN-γ)) as compared to control CD28 or 4-1BB G2 CAR-T cells." (PMID 35053463, 2022).
tumor (continued). "For example, related studies have shown that the activation of T cells requires costimulatory signals produced by the interaction of CD28 and CD86, which could increase the infiltration of T cells in tumor tissue and prolong the survival time of mice." (PMID 36531226, 2022). "We previously observed that the anti-tumor efficacy of combined anti-PD-L1 and anti-TIGIT blockade in mice is abrogated by a CD226-blocking mAb, suggesting that costimulation by both CD226 and CD28 is required to overcome inhibition by PD-1 and TIGIT." (PMID 35263569, 2022). "Since PD-1, ZAP-70, CD28 and CCR7 are all normally expressed in immune cells, the co-expression of these markers may reflect a tumor environment that promotes anti-tumor immunity." (PMID 35203305, 2022). "This study showed that HER2-CAR NK-92 cells (2nd generation CAR, CD28) could recognize and kill HER2+ tumor cells." (PMID 36032149, 2022). "CD28 incorporation into the anti-CD19 CAR structure promotes effector memory maturation, glycolysis, rapid tumor eradication, and T cell exhaustion, whereas 4-1BB signaling induces mitochondrial biogenesis, in vivo T cell persistence, and reprogramming towards a central memory T cell phenotype." (PMID 35628256, 2022). "We showed that tumor-Ag-specific CD8 T cells at the tumor site, which expressed the ICs PD-1, TIGIT, CTLA-4, and TIM-3, as well as CD39, are at an advanced effector memory (CD45RA-CCR7-) differentiation stage and, for the most part, lose CD28 expression." (PMID 35954341, 2022). "Interestingly, the expression of a constitutively active full-length 4-1BB construct together with a CD28 CAR construct (2028Z-4-1BB CAR-T cells) also increased NF-kB signaling, CAR-T cell viability as well as in vivo persistence and anti-tumor activity." (PMID 35053463, 2022). "Given the expression pattern of CD226 and CD28 on CD8+ T cell subsets that likely contribute to a robust response against tumors, optimal activation of the full repertoire of tumor-reactive CD8+ T cells is thus likely to require the coordinate inhibition of both TIGIT and PD-1." (PMID 35263569, 2022). "Additional analysis revealed that significant amounts of IL-2 could be produced by tumor-derived CD4+ and CD8+CD45RA- memory T-cells after combined anti-CD3/anti-CD28 stimulation." (PMID 35474089, 2022). "Certain positive regulatory factors, such as CD27, CD28, CD30, ICOS, and negative regulatory factors, such as CTLA4, PD-1, BTLA, TIM3, andLAG3, at immune checkpoints affect the recognition and apoptotic ability of the immune system against tumour cells." (PMID 36118669, 2022). "Interestingly, even though eliciting the strongest anti-tumor response, the DAP-10/CD27 G3 CAR-T cells tended to be present at lower frequencies compared to CD28 G2 CAR-T cells in vivo." (PMID 35053463, 2022). "Here the authors describe the design of the fusion therapeutic davoceticept (ALPN-202), based on a variant CD80 extracellular domain engineered to bind PD-L1 as well as CD28 and CTLA-4, providing direct T cell costimulation and dual checkpoint inhibition to enable anti-tumor immune responses." (PMID 35379805, 2022). "Next, we employed lineage-specific markers to annotate clusters into major cell types of the tumor, including T cells (CD3G, CD4, CD8A, CD28, and IL7R), B cells (CD19 and CD20), myeloid cells (HLA-DRA and CD14), fibroblasts (THY1 and ACTA2), and tumor cells (EPCAM and S100A)." (PMID 35634306, 2022). "The top differentially expressed gene pathways in tumor-infiltrating double positive cells versus single co-receptor expressing cells from shared clonotypes were related to MHC antigen presentation, CD28 stimulation and TCR signaling, interferon signaling, and PD-1 signaling." (PMID 36185254, 2022). "For optimal T-cell–mediated anti-tumor immunity, T cells must recognize an antigen presented on major histocompatibility complexes (MHC) through the T-cell receptor (TCR) and receive a co-stimulatory signal through CD28 engagement with CD80/CD86." (PMID 36248881, 2022).